SFRP2 (secreted frizzled related protein 2)
Diseases named in the same sentence as SFRP2 in open-access papers (continued):
Sharing a sentence is not in itself a finding about the gene and the disease.
glioblastoma (9 papers, 2012 to 2024). The most malignant astrocytic tumor (WHO grade IV). "The SFRP2 promoter is hypermethylated in around 50% of glioblastomas, which leads to loss of SFRP2 expression." (PMID 35701472, 2022). "In an orthotopic model of glioblastoma, overexpression of SFRP2 was also associated with reduced tumor growth and prolonged survival of mice." (PMID 33140138, 2021). "Indeed, low expression of SFRP2 was associated with a poor clinical outcome in glioblastoma patients." (PMID 33140138, 2021). "SFRP2 transitions cells from a proneural into a mesenchymal glioblastoma gene expression signature, suggesting its involvement in glioblastoma tumor cell plasticity and tumor progression." (PMID 34021259, 2021). "A role in intratumoral heterogeneity is suggested by the spatial distribution or SOX2 and SFRP2 expressing cells in glioblastoma tumors." (PMID 34021259, 2021). "In summary, SOX2-overexpression mirrored the SFRP2-overexpression phenotype and a subgroup of glioblastomas with high SFRP2 and low SOX2 expression was enriched with mesenchymal subtype tumors." (PMID 34021259, 2021). "A subset of patient glioblastoma samples with high SFRP2 and low SOX2 expression was particularly enriched with mesenchymal subtype samples." (PMID 34021259, 2021). "Consistent with our results, miR-22 activated WNT signaling in glioblastoma by targeting Wnt inhibitor SFRP2 and PCDH15." (PMID 34345013, 2021). "Together this suggests an involvement of SFRP2 in the effect of mesenchymal subtype cells on pericytes and macrophages in glioblastoma." (PMID 34021259, 2021). "In conclusion, this work suggests an important role of SFRP2 in the transition from a proneural to a mesenchymal glioblastoma subtype via suppression of SOX2 during tumor progression." (PMID 34021259, 2021). "In a recent study, SFRP2 is found to inhibit sphere formation, cancer stemness and proliferation of glioblastoma cells by acting as an antagonist of SOX2." (PMID 34852024, 2021). "This makes SOX2 and SFRP2 potential key elements in the regulation of glioblastoma subtypes." (PMID 35701472, 2022). "In addition, low SFRP2 expression predicts poor survival of glioblastoma patients, while SFRP2 overexpression reduced tumor growth in mice." (PMID 34852024, 2021). "MiR-522-3p is an oncogene in glioblastoma by targeting SFRP2 through the Wnt/β-catenin pathway." (PMID 34838011, 2021). "This indicated SFRP2 as an inducer of mesenchymal glioblastoma subtype." (PMID 34021259, 2021). "We also analyzed these parameters in highly invasive glioblastoma mesenchymal subtypes and less malignant glioblastoma proneural subtypes after modification of two key genetic elements: SOX2 and SFRP2 recently identified as subtype regulators." (PMID 35701472, 2022). "It was recently described how glioblastoma cells can shift between proneural and mesenchymal subtypes under the influence of two regulatory elements, SOX2 and SFRP2." (PMID 35701472, 2022). "We here show that SFRP2-overexpression decreases CCNE1, CCND1 and CCNB1, and at the same time decreases SOX2 protein and overall cell proliferation in glioblastoma cells." (PMID 34021259, 2021). "SFRP2 was subsequently identified as a SOX2-antagonist, able to induce a mesenchymal glioblastoma subtype signature." (PMID 34021259, 2021). "In connection to previously reported glioblastoma mesenchymal signature transcription factors, SFRP2 increased and correlated with the expression of CEBPB, RUNX1, and FOSL2 in TCGA glioblastomas." (PMID 34021259, 2021). "With regard to previous observations of an active PDGFRA signaling loop in glioblastoma we here experimentally show this can be maintained by SOX2, and subsequently turned off by SFRP2, potentially acting via KLF4." (PMID 34021259, 2021). "Other secreted factors from SFRP2-overexpressing cells, including CXCL12 have been shown important for the recruitment of immune cells in glioblastoma." (PMID 34021259, 2021).
glioblastoma (continued). "In concert with our observed SFRP2-induced pericyte profile, SOX2 expressing glioblastoma cells have been shown in xenograft models to be able to lose SOX2 expression to generate tumor vessel cell structures that resemble pericytes." (PMID 34021259, 2021). "Expression of SFRP2 in cell line U-2987MG resulted in transition to a mesenchymal phenotype with a more specific cytoskeletal organization increasing collective migration and invasion, as SFRP2 has been shown to act as a SOX2 antagonist in glioblastoma cells." (PMID 35701472, 2022). "This work presents SFRP2 and SOX2 as counteracting inducers of gene expression based glioblastoma subtypes, where SFRP2 suppresses SOX2 via non-canonical WNT signaling, KLF4, PDGFRs, and AKT." (PMID 34021259, 2021). "In our co-immunoprecipitation and mass spectrometry analysis for SFRP2-interactors we instead detected other non-canonical WNT-signaling components including VANGL1, a transmembrane protein associated with non-canonical WNT-signaling recently reported to alter cell motility in glioblastoma." (PMID 34021259, 2021). "Regarding previously reported glioblastoma mesenchymal signature transcription factors, SOX2 as opposed to SFRP2, decreased CEBPB and FOSL2 levels consistent with their negative correlation to SOX2 in TCGA glioblastomas." (PMID 34021259, 2021). "As opposed to SFRP2, SOX2 expression was significantly lower in mesenchymal TCGA glioblastoma as compared to classical and proneural tumors." (PMID 34021259, 2021).
multiple myeloma (9 papers, 2011 to 2025). "Secretion of the cytokines Dickkopf 1 (DKK1) and Frizzled related protein 2 (sFRP-2) by myeloma cells contributes to bone resorption as well." (PMID 33634031, 2020). "SFRP2 protein has been reported to be widely expressed by multiple myeloma (MM) cells from patients." (PMID 28794794, 2017). "Bone regeneration is inhibited by myeloma-associated secreted inhibitors like DKK-1, secreted frizzled related proteins 2 and 3 (SFRP2/3), SOST and activin which interfere with osteogenic differentiation pathways." (PMID 24965524, 2014). "In bone marrow samples from multiple myeloma patients, SFRP2 could be detected in 10/14 specimens, while only 1/5 bone marrow samples from patients without bone lesions scored positive for SFRP2 expression." (PMID 33140138, 2021). "DKK1 and sFRP-2 are expressed in multiple myeloma cells of patients with bone lesions." (PMID 33634031, 2020). "Thus, in vitro suppression of the mineralization and alkaline phosphatase activity of osteoblasts has been correlated with sFRP-2 secretion in myeloma cell lines and primary myeloma cells from patients with advanced bone lesions." (PMID 31083455, 2019).
Myocardial fibrosis (9 papers, 2020 to 2025). "Safe-Sfrp2-HuR complex-mediated stability of Sfrp2 mRNA was identified as an underlying mechanism of Safe-regulated myocardial fibrosis." (PMID 37504569, 2023). "In this study, we investigated the association between SFRP2 and myocardial fibrosis, as measured with CMR, among patients with advanced HF." (PMID 32454934, 2020). "Furthermore, we found that the level of SFRP2 was positively associated with myocardial fibrosis, evaluated by cardiovascular magnetic resonance." (PMID 34790288, 2021). "However, it remains unclear whether SFRP2 is a risk factor or a protective compensatory marker of myocardial fibrosis." (PMID 34790288, 2021). "Several potential mechanisms that involved the interaction between SFRP2 and myocardial fibrosis supported our observations." (PMID 40760129, 2025). "SFRP2 regulated myocardial fibrosis and inflammation through the Wnt/β-catenin pathway, which was distincted from the ventricular wall stress pathway reflected by NT-proBNP." (PMID 40760129, 2025). "On the other hand, our study was supported by another prospective cohort study, which provided the message that SFRP2 was a marker of myocardial fibrosis detected by cardiovascular magnetic resonance in HF patients." (PMID 40760129, 2025). "Previous studies emphasize the importance of SFRP2 in myocardial fibrosis and abnormalities of cardiac function." (PMID 40760129, 2025). "Previous studies have demonstrated that SFRP2 facilitates the proliferation of cardiac fibroblasts by activating the Wnt/β-catenin pathway and participates in myocardial fibrosis and cardiac remodeling." (PMID 37334348, 2023). "In fact, although Sfrp2 has traditionally been considered a Wnt inhibitor, its activation has been associated with the increase in the activity of β-catenin pathways, which in the heart of diabetic rats, could have triggered the activation of β-catenin, leading to increased myocardial fibrosis." (PMID 36982322, 2023). "Sfrp2 was demonstrated to improve cardiac function and resist myocardial fibrosis progression after MI." (PMID 34568442, 2021). "This is the first study to report that serum SFRP2, an important Wnt signaling pathway modulator, is an independent marker of myocardial fibrosis." (PMID 32454934, 2020). "Recent studies have suggested that sFRP2 is not only an antagonist of the canonical Wnt signaling pathway, but also has a more complex relationship in myocardial fibrosis, angiogenesis, cardiac hypertrophy and cardiac regeneration." (PMID 32071544, 2020). "An antibody-based SFRP2 blockade strategy can also reduce myocardial fibrosis, increase angiogenesis, and improve cardiac function in the failing hamster heart." (PMID 32454934, 2020). "Recent studies showed that the role of sFRP2 is not only an antagonist for the canonical Wnt signaling pathway, but it also has a more complex relationship with the Wnt pathway in myocardial fibrosis and cardiac regeneration." (PMID 32071544, 2020). "It is possible that sFRP2 plays different roles at different stages of the development of myocardial fibrosis." (PMID 32071544, 2020). "A low concentration of sFRP2 can enhance the effects of Wnt pathway and promote myocardial fibrosis, while a high concentration of sFRP2 can antagonize the Wnt pathway and inhibit myocardial fibrosis." (PMID 32071544, 2020). "It has also been proposed that the effect of SFRP2 on myocardial fibrosis is bidirectional and concentration-dependent." (PMID 32454934, 2020). "Previous studies have shown divergent roles of sFRP2 in myocardial fibrosis, hypertrophy, angiogenesis, cardiac cell death, and regeneration via bi-directional regulation of the canonical Wnt pathway, activation of non-canonical Wnt pathway or modulation of other signaling pathways." (PMID 34722660, 2021).
Myocardial fibrosis (continued). "Since they only enrolled patients with severe decompensated HF and NYHA functional class III–IV, the disparity may be attributed to different stages of HF and the elevated sFRP2 in their study may be a compensatory factor to counteract myocardial fibrosis." (PMID 34722660, 2021). "In our previous study, we observed that SFRP2 is an independent biomarker for myocardial fibrosis." (PMID 34790288, 2021). "In addition, other research also demonstrated that sFRP2 can play a role in reducing myocardial fibrosis via regulating the BMP1 pathway." (PMID 32071544, 2020). "Based on these studies, we propose that sFRP2 may play a similar two-way role in myocardial fibrosis." (PMID 32071544, 2020). "SFRP2 is a novel biomarker of myocardial fibrosis in HF, as measured by ECV fraction." (PMID 32454934, 2020). "How might we explain the apparently inconsistent role of sFRP2 in myocardial fibrosis in these studies?" (PMID 32071544, 2020). "Therefore, we propose that the association of SFRP2 and increased ECV fraction could be reflective of SFRP2 acting as a compensatory factor (rather than a risk factor) to counteract myocardial fibrosis during the development of HF." (PMID 32454934, 2020). "It will be interesting to further examine the potentially unique roles of SFRP2 and SFRP3 in myocardial fibrosis." (PMID 32454934, 2020).
cervical cancer (8 papers, 2009 to 2021). A primary or metastatic malignant neoplasm involving the cervix. "In cervical cancer cell lines, overexpression of SFRP2 was found to decrease nuclear β-catenin levels, and consequently downregulated gene expression of the cell cycle regulators C-myc and Cyclin D1." (PMID 33140138, 2021). "Experimental data confirmed that the Wnt antagonists Secreted Frizzled Related Protein 1 (SFRP1) and Wnt antagonists Secreted Frizzled Related Protein 2 (SFRP2) suppress the EMT of cervical cancer cells through Wnt signaling." (PMID 32758292, 2020). "Previous studies demonstrated that restoration of SFRP1 and SFRP2 expression in cervical cancer cell lines led to the suppression of cancer cell proliferation, transformation and invasion." (PMID 29610564, 2018). "Previous studies revealed that Slug expression inhibits cell apoptosis, in vitro and in vivo, and SFRP2 regulates the expression of Slug in cervical cancer cells." (PMID 23226515, 2012). "Indeed, in cervical cancer it has been shown that expression of sFRP2 attenuates Wnt signaling and suppresses cancer cell growth." (PMID 23352643, 2013).
ovarian carcinoma (8 papers, 2016 to 2024). A malignant neoplasm originating from the surface ovarian epithelium. "Furthermore, our studies revealed that SFRP2 is a potential biomarker for the diagnosis of early-stage ovarian cancer with considerable AUC value and is associated with poor survival rates of OC patients in stages II-IV." (PMID 38069266, 2023). "Taken together, our functional investigations further support a tumour-suppressive role of AHRR and an oncogenic function of SFRP2 in ovarian epithelial cancer." (PMID 38361045, 2024). "The effectiveness of ICIs in ovarian cancer is limited; however, these findings based on the SFRP2+ fibroblast signature provide new insights for the assessment of immunotherapy and offer guidance on whether OC patients are likely to benefit from such treatments." (PMID 38069266, 2023). "SFRP1 SFRP2 and SFRP5 are methylated in ovarian cancer, and experimental overexpression or knockdown, demonstrated that epigenetic silencing of SFRP5 was related to tumour growth, invasion (via EMT) and chemosensitivity in ovarian cancer." (PMID 27196929, 2016). "In five ovarian cancer cell lines, SFRP2 did not inhibit WNT signalling and more interestingly, in one cell line, SFRP2 activated WNT signalling." (PMID 38361045, 2024).
pancreatic cancer (8 papers, 2016 to 2025). "A network mapping of direct and indirect relationships between KIF5B and SFRP2 was done by overlaying their connective map with pathways that are regulated by pancreatic cancer." (PMID 36002889, 2022). "KIF5B and SFRP2 show promise for early detection and investigation in progressive pancreatic cancer." (PMID 36002889, 2022). "Among all the proteins that were analyzed (MMP3, KIF5B, SFRP2, and LOXL2), KIF5B and SFRP2 show promise as bona fide early pancreatic cancer biomarkers expressed in progressive stages of pancreatic cancer." (PMID 36002889, 2022). "Proteomic characterization of EVs mimicking “first contact” conditions of tumor-stromal interactions resulted in the identification of KIF5B and SFRP2 as promising early biomarkers that are expressed in progressive stages of pancreatic cancer." (PMID 36002889, 2022). "Additionally, a human TMA was used to analyze the expression of KIF5B and SFRP2 in progressive stages of pancreatic cancer." (PMID 36002889, 2022). "All these findings suggest that KIF5B and SFRP2 are promising early pancreatic cancer markers." (PMID 36002889, 2022). "CRISPR–Cas9-based genome editing provides a new therapeutic strategy with high specificity, such as the dCas9-multiGCN4/scFv-TET1CD-sgRNA-based SFRP2-targeted demethylation system provides a SFRP2-targeting therapeutic strategy to inhibit pancreatic tumor metastasis." (PMID 31399111, 2019). "A network prediction mapping analysis was performed to investigate pancreatic cancer-related pathways that are activated on the activation of both KIF5B and SFRP2." (PMID 36002889, 2022). "The mRNA expression levels of SFRP2 and SFRP4 were significantly elevated in the breast, gastric, and pancreatic cancer tissues, while SFRP1 showed significantly decreased expression in datasets from 15 different types of cancer." (PMID 34205081, 2021). "For therapy of pancreatic tumor patients with TET1 low expressing, our finds provide potential targets including TET1 and its downstream gene SFRP2 for therapy." (PMID 31399111, 2019). "TET1 binds to the SFRP2 promoter and catalyzes demethylation to activate SFRP2 transcription, inhibiting the Wnt signaling pathway and ultimately obstructing EMT in pancreatic tumors." (PMID 31399111, 2019). "TET1 binds to the secreted frizzled-related protein 2 (SFRP2) promoter and catalyses its demethylation to activate SFRP2 transcription, thereby repressing the Wnt/β-catenin signalling pathway and ultimately restraining the epithelial-mesenchymal transition (EMT) in pancreatic tumours." (PMID 34656178, 2021). "Cell-free DNA hypermethylation of BMP3, MESTv2, SST, TFPI2, TAC1, ALX4, HIC1, SFRP2, SEPT9v2 and WNT5A has not previously been described in the literature in relation to pancreatic cancer." (PMID 27891190, 2016). "TET1 bound to the secreted frizzled-related protein 2 (SFRP2) promoter and catalyzed demethylation to activate transcription of SFRP2, inhibiting both the canonical and non-canonical Wnt signaling pathways, and ultimately obstructing epithelial-mesenchymal transition (EMT) in pancreatic tumors." (PMID 31399111, 2019).